IL13 (interleukin 13)
Diseases named in the same sentence as IL13 in open-access papers (continued):
Sharing a sentence is not in itself a finding about the gene and the disease.
Pruritus (continued). "Interleukin (IL)-4, IL-13, and IL-31 play crucial roles in pruritus; therefore, their inhibition is a key therapeutic strategy." (PMID 40568299, 2025). "Across disorders, pathway-directed biologics against IL-4Rα, IL-13, and IL-31R consistently reduce disease activity and pruritus in AD and prurigo nodularis, with emerging signals of benefit in bullous pemphigoid and chronic spontaneous urticaria." (PMID 41226755, 2025). "Along with a reduction in pruritus intensity, patients receiving anti-IL-13 also reported improved sleep quality." (PMID 38541978, 2024). "During a 16-week-long observation, the patients treated with anti-IL-13 were more likely than placebo to report a reduction in pruritus intensity of at least 4 points in the weekly average of worst daily Pruritus NRS compared with baseline." (PMID 38541978, 2024). "Research reports examining cytokines in the skin of patients with ICI-induced cutaneous symptoms have found increased production of Th2 cytokines such as IL-4, IL-5, and IL-13 in cases of urticaria, pruritus, and eczema." (PMID 39200350, 2024). "Regarding pruritus, IL-4 and IL-13 are suggested to act on IL-4Ra expressed on peripheral nerves, transmitting chronic pruritus through the Janus kinase (JAK) 1 signaling pathway." (PMID 38590314, 2024). "IL-31 is a key player in the pathogenesis of pruritus, both in the acute and in the chronic stages, and its signaling pathway is closely regulated by IL-4 and IL-13." (PMID 38398754, 2024). "Subsequently, the actions of IL-4 and IL-13 drive the production of IgE, whereas IL-31 induces pruritus." (PMID 39717308, 2024). "The findings suggest a pivotal role of IL-4 and IL-13, along with IL-13RA1, in pruritus pathogenesis in both entities, while IL-13 upregulation in AD is countered by IL-13RA2." (PMID 39126011, 2024). "The pathogenesis of AD and pruritus in AD patients are both significantly influenced by the cytokines IL-4 and IL-13." (PMID 36983094, 2023). "Nevertheless, additional research has demonstrated that IL-4 and IL-13 can both directly activate pruritus in mice, and that applying mixtures of these mediators even increased the induction of itch." (PMID 36983094, 2023). "The TSLP and IL-13, which are key factors in AD's pathogenesis, mediate pruritus, the main AD symptom." (PMID 37790739, 2023). "It appeared that TLR2 can upregulate peripheral IL-13Rα2 expression, which led to exaggeration of IL-13-mediated pruritus suggesting that peripheral TLR2-IL-13Rα2 signaling can cause itching sensation and enable neurogenic inflammation." (PMID 37834183, 2023). "In a phase 2b, placebo-controlled, double-blind trial, as early as day 2 in the higher-dosage group, the humanized high-affinity IL-13 antibody lebrikizumab significantly reduced the severity of AD and the intensity of pruritus." (PMID 36983094, 2023). "In this regard, it has been shown recently that targeting IL-13 and IL-4 using the monoclonal antibody dupilumab resolves pruritus and inflammatory skin lesions in BP, indicating a role of neuroimmune interaction mechanisms with immune cells." (PMID 36979421, 2023). "Transgenic mice with epidermis overexpressing IL-4 and IL-13 exhibited AD-like symptoms, including skin lesions and pruritus, and both IL-31 transgenic mice and wild-type mice treated with IL-31 developed hallmark features of AD and scratching behavior." (PMID 36232673, 2022). "These itch‐specific iNCs were responsive to AD driver cytokines (IL4/IL‐13) as indicated by calcium imaging." (PMID 35111948, 2022). "It has been reported that IL-13 highly stimulates TRPA1 expression in mast cells and IL-31-induced pruritus decreased in TRPA1-deficient mice." (PMID 35563259, 2022). "Several Th2 cytokines can contribute to pruritus during scabies, including IL-4, IL-13 TSLP, IL-31, and periostin." (PMID 33807098, 2021). "Cytokines that are important for pruritus in AD (e.g., IL-31, IL-4, IL-13, and TSLP) transmit their signals via JAK-1 and JAK-2 into the cells." (PMID 34026782, 2021).
Pruritus (continued). "This is underscored by the fact that clinical symptoms and pruritus in AD are significantly improved by the anti-IL-4 receptor α (IL-4Rα) antibody dupilumab, which inhibits both IL-13 and IL-4 signaling." (PMID 33233866, 2020). "By targeting the interleukin 4 (IL-4)/IL-13 pathway, it rapidly controls pruritus and blistering." (PMID 41466952, 2025). "Type 2 cytokines such as IL-4, IL-13, and IL-31 sensitize cutaneous sensory neurons, lowering their activation thresholds and fueling pruritus, which in turn provokes scratching that further disrupts the barrier, releases additional alarmins, and amplifies local immune responses." (PMID 40725651, 2025). "IL-31 directly induces pruritus, while IL-4 and IL-13 enhance itching." (PMID 40109398, 2025). "Furthermore, in mice, an injection with IL-4, IL-13, and a combination of both led directly to acute pruritus." (PMID 39126011, 2024). "A possible mechanism for this is that IL-33 promotes pruritus via a pathway involving IL-13 production, which may enhance histamine-induced pruritus." (PMID 39063153, 2024). "Current evidence suggest IL-13 as a crucial cytokine AD pathogenesis, supporting its significant contribution in mediating several clinical features, including skin inflammation and pruritus." (PMID 37144036, 2023). "IL-4, IL-33, and IL-13 as well as neuropeptides (BNP, ET-1) increase the expression of TSLP on keratinocytes, opening the door for additional pathogenic pathways to be associated with pruritus." (PMID 37511610, 2023). "By blocking IL-4 and IL-13 on sensory neurons and inhibiting IL-31 production, it may decrease pruritus in PLCA patients as well." (PMID 38137741, 2023). "IL‐13, rather than IL‐4, induces recruitment of eosinophils;66 therefore, IL‐13 is speculated to induce pruritus not only through direct stimulation of sensory nerve fibers but also through eosinophil‐mediated mechanisms." (PMID 36477831, 2023). "The oral JAK1 inhibitor upadacitinib might suppress the effects of IL-31 or IL-4/IL-13 and block the communication between nerves and eosinophils, leading to the suppression of pruritus." (PMID 36983203, 2023). "This may suggest that IL-13 and its receptors are important for regulating skin barrier dysfunction and pruritus in AD." (PMID 37834183, 2023). "Pruritus is mainly stimulated by networked communication between the cutaneous immune system, nervous system, and epidermal keratinocytes and can be alleviated by immunosuppressants, or targeted antibody therapy (e.g., anti IL-4/13, anti-IL13, anti-IL31)." (PMID 37511610, 2023). "The inhibition of JAK ensures the inhibition of receptors; therefore, the subsequent biological effects, from a greater number of cytokines, are variably involved in the pathogenesis of pruritus, not only IL13 and IL4 but also IL31, IL2, IL8, IL25, IL33, IFNγ and thymic stromal lymphoprotein (TSLP)." (PMID 35890180, 2022). "Mediators which could be directly involved in the venom-induced pruritus include histamine and tryptase released from mast cells, interleukin-4 and interleukin-13 from Th2 lymphocytes, as well as leukotriene C4." (PMID 35387042, 2021). "Th-2 profile cytokines, such as IL-4, IL-5 and IL-13, play a significant role in the pathogenesis of the disease by switching the immunoglobulin class to IgE and stimulating afferent neurons via IL-4Rα, thereby promoting pruritus." (PMID 34948183, 2021). "However, other studies have shown that both IL-4 and IL-13 also can directly stimulate pruritus in mice and that the application of combinations of these mediators even accelerated itch induction." (PMID 34026782, 2021). "In sum, type-2 immune responses and key-cytokines (IL-2, IL-4, IL-13, IL-31) are critically involved in the chronic phase of pruritus pathophysiology, mediating peripheral sensitization mechanisms and abnormal neuro–immune–epithelial cross-talk in several pruritic conditions." (PMID 33807098, 2021).
Pruritus (continued). "Besides, it has been reported that transgenic mice expressing IL-13 in skin develops intense pruritus." (PMID 28265582, 2017). "Based on the available literature, eosinophils, IgG autoantibodies, IgE autoantibodies, SP and its receptor NK1R, IL-31 and its receptor OSMRb, IL-31RA, IL-13, IL-4, periostin, and basophils may be responsible for pruritus in BP and could be potential therapeutic targets." (PMID 39459488, 2024). "In addition, IL-4 and IL-13 together induce the conversion of immunoglobulins to IgE in B cells and stimulation of afferent neurons via the IL-4 receptor subunit-α (IL-4Rα) to promote pruritus." (PMID 39697554, 2024). "The available evidence strongly indicates that TSLP, IL-13 and IL-1ß are the key cytokines involved in the pathogenesis of AD, with these cytokines playing a substantial role in mediating various clinical manifestations of AD, including skin inflammation and pruritus." (PMID 38817611, 2024). "Since novel therapeutic targets, including anti-IL-4/IL-13 and anti-IgE, have successfully been used, immunological pathways are suggested to play an important role in the mechanism of pruritus in AIBD and may be used to target pruritus and overall disease activity in these patients." (PMID 36979421, 2023). "Cytokines IL-4 and IL-13, primarily produced by Th2 cells and ILC2s (Group 2 Innate Lymphoid Cells), directly sensitize TRPA1 on sensory neurons, promoting pruritus." (PMID 41596464, 2026). "In conclusion, the LK5 herbal complex has anti-inflammatory properties that reduce LPS- and IL-4/IL-13-induced inflammation, and has anti-AD effects in animal models of DNCB-induced AD and compound 48/80-induced pruritus." (PMID 38258052, 2023). "Cytokines including IL-31, IL-4, IL-13, and TSLP are crucial for pruritus in AD transmit their signals into the cells via JAK-1 and JAK-2." (PMID 36983094, 2023). "JAK/STAT-mediated production of cytokines including IL-4, IL-13, IL-31, and TSLP inhibits the expression of important skin barrier proteins and triggers pruritus in AD." (PMID 35889539, 2022). "Histamine, IL-33, IL-31, IL-4, IL-13, and thymic stromal lymphopoietin (TSLP) have been suggested to be mediators of pruritus in AD." (PMID 35163297, 2022). "IL-31, IL-4, IL-13, TSLP, and IL-5, as well as other cytokines influence inflammation and pruritus in AD." (PMID 34026782, 2021). "IL-4 and IL-13 directly activate TRPA1+ sensory neurons via IL-4Rα, leading to chronic pruritus." (PMID 41596464, 2026). "Conversely, chronic pruritus frequently involves non-histaminergic mechanisms, driven by cytokines such as interleukin-4 (IL-4), interleukin-13 (IL-13), and particularly interleukin-31 (IL-31)." (PMID 41166019, 2025). "After binding to receptors, both IL-4 and IL-13 activate the JAK/STAT (Janus kinase/signal transducer and activator of transcription) signaling pathway; therefore, blocking this pathway substantially reduces pruritus intensity in the course of AD." (PMID 38541978, 2024). "JAK1 inhibition represents a good therapeutic strategy for patients suffering from significant pruritus and patients with an intense itch that does not respond to IL-4 receptor inhibitors, IL-13 inhibitors, and IL-31 receptor inhibitors." (PMID 36839707, 2023). "The number of IL‐13 positive cells, but not IL‐4 positive cells, in the dermis correlated with the severity of pruritus in BP." (PMID 36477831, 2023). "As IL-13/IL-4 activate JAK1–STAT6, JAK1 inhibitor reduces pruritus mediated by IL-31 or IL-13/IL-4." (PMID 33233866, 2020). "Although IL-13/IL-4 have been reported not to induce acute pruritus, a recent study proved that they act as pruritogens and induce scratching behavior." (PMID 33233866, 2020). "Similarly, CGRP stimulates the release of IL-13 from circulating CLA+ T-cells in AD; an increased IL-13 release from T-cells has been observed in more severely affected AD patients with more intense pruritus." (PMID 34026782, 2021).
Pruritus (continued). "Hence, results of the present study indicate that the studied cytokines- IL-13, IL-31 and TNF-α, have key role in the pathogenesis of canine AD and expression of IL-13 and TNF-α genes in atopic dogs might be down-regulated with increased severity of pruritus." (PMID 34075152, 2021). "Th2 cells produce IL-4 and IL-13 driven by the transcription factor GATA3, which can not only induce macrophage polarization to the M2 phenotype but also induce TGF-β1 and collagen synthesis through the JAK-STAT signaling pathway and induce pruritus." (PMID 37705977, 2023).
schistosomiasis (63 papers, 2005 to 2025). An infectious disease caused by parasitic trematodes of the genus Schistosoma that colonize human blood vessels and release eggs that can cause granulomatous reactions leading to acute (swimmer's itch or acute schistosomiasis syndrome) or chronic disease. "Cytokines like IL‐11 or IL‐13 are known to be master regulators of fibrosis, especially in schistosomiasis‐associated fibrogenesis." (PMID 40751475, 2025). "The chromosome 5q31–q33 Th2 cluster gene, which regulates the synthesis of interleukin 13, interleukin 4, and interleukin 5, is primarily linked to an increased risk of developing schistosomiasis." (PMID 41179539, 2025). "Both in acute infections and in the chronic stage, the functional IL13 promoter polymorphism represented an increased risk for advanced schistosomiasis." (PMID 37629063, 2023). "Since Th2 cytokines such as IL-4, IL-5, and IL-13 are implicated during schistosomiasis, it is worthy to evaluate such interleukins during the coinfection with human African trypanosomiasis." (PMID 37954132, 2023). "Tissue fibrosis (scarring) is central to schistosomiasis associated pathology, particularly in the liver, with IL-13 proposed as the main pro-fibrotic mediator in mice." (PMID 35958580, 2022). "Specifically, TH2-associated cytokines IL-4, IL-5, IL-10, and IL-13 from splenic cell preparations appeared elevated in offspring exposed to treated maternal schistosomiasis." (PMID 35833137, 2022). "Type 2 cytokines (i.e., IL-4 and IL-13) are typically associated with the granulomatous response to parasite eggs in schistosomiasis." (PMID 35954255, 2022). "Within the schistosomiasis uninfected group, CC and CT variants had significantly (p<0.05) higher IL-13 levels; median 135.0 pg/mL and 113.6 pg/mL, respectively compared to TT variant individuals; 47.15 pg/mL." (PMID 34048465, 2021). "Our study evaluated the frequency of the IL-13 rs1800925/-1112 C/ T promoter single nucleotide polymorphisms (SNPs) among schistosomiasis infected individuals and assessed the association of the variants on IL-13 cytokine levels." (PMID 34048465, 2021). "The genes with the largest literature were the Th2 cytokine genes originally identified by Marquet in SM1 (IL3, IL4, IL5, IL9, and IL13), that each had between 17 and 511 publications associated with schistosomiasis." (PMID 33659002, 2021). "Distribution and association of IL-13-1112C/T genotype and allelic frequencies in schistosomiasis infected and uninfected participants." (PMID 34048465, 2021). "The results illustrated that IL13-1112CT genotype exhibited the most frequent distribution among the study population and there were higher schistosomiasis prevalence and infection intensity of individuals with IL13-1112CT variant." (PMID 34048465, 2021). "We investigated IL-13 rs1800925/-1112 C/T promoter single nucleotide polymorphisms and susceptibility to schistosomiasis." (PMID 34048465, 2021). "Within the schistosomiasis infected group, CC, CT and TT variant individuals had insignificant differences of IL-13 level." (PMID 34048465, 2021). "Along with providing evidence for some degree of SNP inheritability, they also acknowledged that IL13-1055T/T was associated with protection against schistosomiasis, as compared to IL13-1055C/T and IL13-1055C/C." (PMID 34185775, 2021). "Apparently, IL-13-1112C variant individuals were more susceptible to schistosomiasis whereas individuals with IL-13-1112T variant were protected against infection." (PMID 34048465, 2021). "Risk of prostate cancer development (PSA > 4 ng/mL and < 4ng/mL) association to schistosomiasis status, IL-13 cytokine concentration and IL-13 rs1800925 variants." (PMID 34048465, 2021). "IL-4/IL-13 signalling in pulmonary tissue from individuals who died of schistosomiasis associated- pulmonary hypertension, underscoring the potential clinical relevance." (PMID 31024947, 2019).